PLK1 (polo like kinase 1)
Diseases named in the same sentence as PLK1 in open-access papers (continued):
Sharing a sentence is not in itself a finding about the gene and the disease.
renal carcinoma (6 papers, 2017 to 2024). A carcinoma arising from the epithelium of the renal parenchyma or the renal pelvis. "Elevated levels of PLK1 have been reported in multiple cancer types, including melanoma, prostate, breast, colorectal, and renal cancer." (PMID 29186071, 2017). "Intriguingly, despite the expressions of BID, CDKN3, and PLK1 being consistently higher in the renal carcinoma cell lines than in the normal renal cells across both the primary and tenth passages, shifts in the gene expression levels among the carcinoma lines were noted." (PMID 38953023, 2024). "To investigate whether PLK1 inhibition induces apoptosis and cell cycle arrest in human renal carcinoma Caki cells, we assessed cell cycle, the apoptotic hypo-diploid sub-G1 phase, and the cleavage of PARP." (PMID 29186071, 2017). "The results of the TCGA-KIRC cohort showed that either in paired or unpaired renal cancer tissues, except for CLIC5, which was in a low expression state, the remaining four genes (MXD3, NUF2, PABPC1L, and PLK1) were in a high expression." (PMID 38546385, 2024). "As a result, the optimized complex exhibited a dose-dependent silencing capability of the polo-like kinase 1 (PLK-1) gene, a well-known proto-oncogene in the human renal carcinoma cell (OSRC-2) line, with no appreciable cytotoxicity." (PMID 29296128, 2018).
viral infection (6 papers, 2008 to 2024). "Since increased cell death and cytokine expression induced by virus infection limit virus replication, it is possible that targeting PLK1 can enhance host innate immune responses, leading to a novel strategy to control virus infection." (PMID 19629176, 2009). "To further examine the role of PLK1 in viral gene expression, we used a mini-genome system, in which viral gene expression can be examined free of viral infection." (PMID 19629176, 2009). "Since PLK1 plays a critical role in cell cycle progression, this long period of PLK1 depletion, coupled with viral infection, is overwhelmingly cytotoxic." (PMID 19629176, 2009). "The lower viral gene expression after PLK1 phosphorylation may also favor persistent viral infection." (PMID 19629176, 2009). "Moreover, vpr and vif single mutant virus infections, which caused little or no attenuation in G2,M arrest activity, respectively, also reduced Plk1 and centrin association with 14-3-3 θ, although less than wild-type virus." (PMID 18445273, 2008). "Our findings suggest that PLK1 could be an attractive immunotherapeutic target antigen for cancer immunotherapy, and that similar strategies would be applicable for the optimisation of cancer vaccines for the treatment of numerous viral diseases and malignant tumours." (PMID 32595211, 2020).
acute leukemia (5 papers, 2015 to 2022). A clonal (malignant) hematopoietic disorder with an acute onset, affecting the bone marrow and the peripheral blood. "PLK1 has been implicated in a number of acute leukemias and is expressed in a range of infant and pediatric ALLs, with levels being particularly high in samples from relapsed infants with MLL-AF4+ ALL." (PMID 34706236, 2021). "Regarding mitotic inhibitors in acute leukemias, preclinical data suggest a very good response of complex karyotype AML to PLK1 inhibition and of cohesion-mutated AML to disruption of APC/CCDC20 function." (PMID 31771633, 2019). "Several studies have shown the efficacy of PLK1 suppression by small interfering RNA or selective PLK1 small molecule inhibitors in acute leukemia cells." (PMID 31771633, 2019). "Recently, the polo-like kinase 1 (PLK1) inhibitor has showed promising effects in the treatment of acute leukemia." (PMID 25574601, 2015). "PLK1 is a serine/threonine-protein kinase expressed during mitosis and overexpressed in multiple cancers, including acute leukemia." (PMID 25574601, 2015).
adenoma (5 papers, 2018 to 2022). A neoplasm arising from the epithelium. "Denkert’s group reported that whereas normal colon mucosa and adenomas showed only a weak expression of PLK1, 66.7% of carcinomas showed instead a strong expression of PLK1." (PMID 34065438, 2021). "Sample AC6 was re-dissected into two adenoma regions (A1, A2) of different grades and two carcinomas (C1, C3) of different stages, with public mutations of APC, KRAS, and PLK1 found in all four regions." (PMID 32895052, 2020). "Because ApcMin/+ mice typically develop adenomas in the small intestine by 3 months of age, we wondered how Plk1 silencing influences tumor development." (PMID 29549256, 2018). "Unbiased analysis of the MYC targets V2 gene set revealed clusters correlated with the tumor histopathology, and adenocarcinoma-derived PDOs exhibited the high expression of distinct genes from adenoma-derived PDOs related to cellular proliferation, including CDK4, PLK1 and 4, MCM4, and MYC." (PMID 33060766, 2020).
adrenocortical carcinoma (5 papers, 2016 to 2024). "Another phase I trial evaluated the activity of polo-like kinase 1 (PLK1) siRNA (TKM-080301) in patients with refractory adrenocortical cancer." (PMID 35681657, 2022).
colorectal tumors (5 papers, 2014 to 2025). "High RPL27 expression was found to promote colorectal tumour cell proliferation and stemness in vitro and in a mouse xenograft model via polo-like kinase 1 (PLK1) signalling." (PMID 40940922, 2025). "Highly enriched PLK1 signaling was further confirmed in pairs of colorectal tumors with matched normal mucosa from the CIT cohort (GSE39582) and TCGA cohort (COAD & READ)." (PMID 34881526, 2021). "For example high level gain was observed at 20q where AURKA is located, frequent gain at 16p (PLK1), and loss at 4q (MAP9) in a number of colorectal tumors." (PMID 24876664, 2014). "Similar data have been retrieved by using the PLK1 inhibitor Volasertib (BI6727) in the APCmin/+ strain and also in human cells derived from colorectal tumors that express a truncated APC version." (PMID 30862113, 2019). "In parallel, GEO data set analyses (GDS 2947) of colorectal tumors and adjacent normal tissue show downregulation of MAP9 and upregulation of AURKA and PLK1, with values that are similar to what we observed in this study." (PMID 24876664, 2014). "We show here that, in colorectal tumors, MAP9 is strongly underexpressed whereas AURKA and PLK1 are overexpressed." (PMID 24876664, 2014).
diffuse large B-cell lymphoma (5 papers, 2017 to 2024). "The cytotoxicity of the Ras-mimetic PI3K/PLK1 inhibitor rigosertib in diffuse large B-cell lymphoma (DLBCL) cells was associated with MYB suppression and inhibition of nuclear MYB translocation by sumoylation." (PMID 38835346, 2024). "PLK1 was suggested as a promising predictive biomarker for diffuse large B-cell lymphoma." (PMID 35251139, 2022). "Interactions between the polo-like kinase 1 (PLK1) inhibitor volasertib and the histone deacetylase inhibitor (HDACI) belinostat were examined in diffuse large B-cell lymphoma (DLBCL) and mantle cell lymphoma (MCL) cells in vitro and in vivo." (PMID 28416758, 2017).
Ewing sarcoma (5 papers, 2010 to 2025). A small round cell tumor that lacks morphologic, immunohistochemical, and electron microscopic evidence of neuroectodermal differentiation. "Our biogenic analysis further corroborates the close association between PRC1 and the PLK1 signaling pathway, aligning with findings from prior research on Ewing's sarcoma." (PMID 40093809, 2025). "Other than shaping the TME, we found that PRC1 was associated with the PLK1 pathway, which was in accordance with previous studies in Ewing sarcoma (EwS)." (PMID 35983074, 2022). "In this study, we investigated the molecular mechanisms of eribulin-induced cell death and its therapeutic potential in combination with the PLK1 inhibitor BI 6727 in Ewing sarcoma (ES)." (PMID 28881742, 2017). "In this study, we chose three genes STK10, TNK2 and PLK1 for further validation studies as these genes were prioritized by having significant Z-score values for both siRNAs across all screens in the four Ewing's sarcoma cell lines." (PMID 20718987, 2010). "We confirmed the effects of silencing of STK10, TNK2, and PLK1 on growth and survival of Ewing's sarcoma cells by repeating the cell based assay in 384-well plates using a different lot of siRNA having the same sequences as the kinase library siRNA." (PMID 20718987, 2010). "Silencing of STK10, TNK2 and PLK1 by both siRNA sequences inhibited cell growth in the four Ewing's sarcoma cell lines as measured by cell number." (PMID 20718987, 2010). "PLK1 is a well-described therapeutic target in multiple types of cancer, including Ewing sarcoma." (PMID 38933441, 2024). "Heat map of the Z-scores shows specificity of these 16 siRNA for decreasing cell number in Ewing's sarcoma cells only as opposed to a global lethal siRNA targeting PLK1 (polo like kinase 1) that also reduces proliferation of normal fibroblast cells." (PMID 20718987, 2010). "We confirmed that PLK1 knockdown led to increased cell death, but did not appear to be specific to Ewing's sarcoma cells as it was also a significant "hit" for normal fibroblasts." (PMID 20718987, 2010).
myelodysplastic syndrome (5 papers, 2015 to 2025). A clonal hematopoietic disorder characterized by dysplasia and ineffective hematopoiesis in one or more of the hematopoietic cell lines. "The most promising results come from studies evaluating the use of PLK1 inhibitors in the treatment of myelodysplastic syndrome (MDS) and AML." (PMID 40111122, 2025). "Rigosertib inhibits both PLK1 and phosphatidylinositol 3-kinase (PI3K) and has been investigated in clinical trials against solid tumors and hematological malignancies such as myelodysplastic syndrome (MDS)." (PMID 26008977, 2015).
oral cancer (5 papers, 2016 to 2021). "The long-term effects of the siRNA against PLK1 on the colony formation of oral cancer cells were examined with a clonogenic assay." (PMID 31387297, 2019). "Further clinical trials are required to validate the antitumor effects of BI2536 and determine its potential use as a PLK1 inhibitor for oral cancer treatment in the future." (PMID 29765534, 2018). "Downregulation of PLK1 expression thus provides a potential mechanism for mitotic arrest and subsequent apoptosis in response to ER maleate in oral cancer cells." (PMID 26934445, 2016). "To assess the clinical significance of Syk and PLK1 in oral cancer, we compared nuclear (N) and cytoplasmic (C) expression levels of Syk and PLK1 proteins in normal oral mucosa and OSCCs." (PMID 26934445, 2016). "Taken together, it is likely that inhibition of PLK1 actively contributes to ER maleate driven oral cancer cell death by modulating these pathways." (PMID 26934445, 2016). "Although PLK1 is frequently reported as an oncogene, the co-expression of PLK1 with specific genes could also play a tumor suppressor role and contribute to tumor progression by inhibiting the growth of oral cancer cells." (PMID 34575686, 2021). "Further, these effects were partially rescued by overexpression of PLK1 in oral cancer cells." (PMID 26934445, 2016). "However, PLK1 as a critical mediator in oral cancer development remains to be examined." (PMID 26934445, 2016). "Silencing PLK1 with the siRNA significantly suppressed colony formation in both SAS and TW2.6 oral cancer cells." (PMID 31387297, 2019). "Interestingly, PLK1 effect is modulated by PI3K-Akt-mTOR and MAPK pathways, both of which we have shown here were affected by ER maleate in oral cancer cells." (PMID 26934445, 2016). "BI6727 largely caused a G2-M phase arrest in cell cycle progression, whereas it did not affect sub-G1 phase, suggesting that PLK1 inhibition-reduced cell proliferation might mainly occur through a cell cycle arrest at G2-M phase in oral cancer cells." (PMID 31387297, 2019).
stomach cancer (5 papers, 2012 to 2024). "With this approach we identified MDM2 ligase, coupled with inhibitors of the targets BCL2L1, BRD4, CDK9, PLK1 and MCL1 in stomach tumor tissue, as a therapeutic strategy." (PMID 35249548, 2022).
asthma (4 papers, 2018 to 2025). "The control of these muscle cells has been connected to asthma, where the overexpression of PLK1 was correlated with an increase in asthma and inflammation of pulmonary cells." (PMID 40725399, 2025). "Moreover, the expression of miR-509 is lower in human asthmatic ASM cells, which is responsible for the upregulation of Plk1 and asthma progression." (PMID 36078171, 2022). "Smooth muscle conditional KO of Plk1 inhibits asthma progression in a murine model of asthma." (PMID 36078171, 2022). "In contrast, Plk1 mRNA was increased in asthmatic HASM cells (control = 5, asthma = 4, p < 0.05, t-test)." (PMID 30135525, 2018). "Moreover, Plk1 protein expression was higher in asthmatic HASM cells (control = 5, asthma = 4, p < 0.05, t-test)." (PMID 30135525, 2018). "However, Plk1 does not affect Th2 inflammation in experimental asthma." (PMID 36078171, 2022).
B-cell lymphoma (4 papers, 2021 to 2025). "PLK1 is also considered as an oncotarget for aggressive B‐cell lymphomas since it stabilizes MYC." (PMID 34605140, 2021). "Both Plk1 and Foxm1 are promising therapeutic targets in B-cell lymphoma." (PMID 34363012, 2021). "Although c-MYC signaling is associated with aggressive neoplasms, we recently demonstrated the prevalence of c-MYC/PLK1 signaling in nodular lymphocyte predominant B-cell lymphoma (NLPHL), an indolent B-cell lymphoma subtype." (PMID 41008822, 2025).
Bladder Urothelial Carcinoma (4 papers, 2017 to 2022). "For example, PLK1 signaling pathway, a key regulator of cell division, was significant in Bladder Urothelial Carcinoma (adjusted p < 0.0001) and liver hepatocellular carcinoma (adjusted p = 0.01)." (PMID 34319007, 2021). "In our previous studies, PLK1 expression status closely correlated with important histopathologic characteristics (grades and stages) and the recurrence and metastasis of bladder urothelial carcinomas." (PMID 27878946, 2017).
cholangiocarcinoma (4 papers, 2019 to 2022). A carcinoma that arises from the intrahepatic biliary tree (intrahepatic cholangiocarcinoma) or from the junction, or adjacent to the junction, of the right and left hepatic ducts (hilar cholangiocarcinoma). "Thus, taking advantage of targeting and intervening in mutual PLK1 on cholangiocarcinoma cells and CAFs and exploring the underlying mechanism hold great potential for treating CCA." (PMID 35664077, 2022). "Subsequently, biogenic analysis of human tissue and murine models together with in vitro and in vivo experimental data indicated that polo-like kinase 1 (PLK1) played a significant role in the cell cycle in cholangiocarcinoma cells." (PMID 35664077, 2022). "Notably, both TPX2 and PLK1 were among the top 20 correlated genes with AURKA in the TCGA dataset of cholangiocarcinoma based on Person correlation analysis." (PMID 32127951, 2020). "In addition, a PLK1 inhibitor (Ro3280) loaded dual-targeting drug delivery system (AA-HA-ODA) was prepared and exhibited high affinity for CAFs and cholangiocarcinoma cells." (PMID 35664077, 2022). "In summary, the feasibility of the proposed strategy that targeting and intervening the mutual PLK1 on both CAFs and the inner CCA tumor cells by targeting AA-HA-ODA sequentially was verified, which might provide enlightenment for clinical cholangiocarcinoma treatment." (PMID 35664077, 2022). "We sought to confirm the co-expression of TPX2, PLK1 and AURKA in cholangiocarcinoma datasets." (PMID 32127951, 2020).
chronic myeloid leukemia (4 papers, 2012 to 2024). "Recent data shows that the combination therapy of TG-101348 and BI-2536 (PLK1 inhibitors) synergistically targets oncogenic pathways and that the combination therapy of TG101348 and imatinib (ABL kinase inhibitor) inhibits cell proliferation of BCR-ABL-positive chronic myeloid leukemia cells." (PMID 25869210, 2015).
Fanconi anemia (4 papers, 2014 to 2025). Fanconi anemia (FA) is a hereditary DNA repair disorder characterized by progressive pancytopenia with bone marrow failure, variable congenital malformations and predisposition to develop hematological or solid tumors. "For example, a module composed of a FoxM1 transcription factor network, an E2F transcription factor network, Aurora B kinase signaling, ATR signaling, PLK1 signaling, and members of the Fanconi anemia DNA damage response pathway was densely connected." (PMID 29988723, 2018). "At the same time, the ATR (ataxia telangiectasia and Rad3-related) pathway, PLK1 (polo-like kinase 1) pathway and the Fanconi anemia pathway showed the ability to repair DNA damage in cancer cells." (PMID 24564407, 2014).
gastric adenocarcinoma (4 papers, 2010 to 2023). "BORA, as the key intermediate protein of Aurora A and PLK1, was reported to be a potential biomarker for prognosis in lung, breast, and gastric adenocarcinomas." (PMID 32655322, 2020). "We now show that there is also coordinate overexpression of FOXM1 and PLK1 in gastric adenocarcinomas, thereby providing the potential for feedback potentiation of FOXM1 activity." (PMID 26576650, 2015). "This study has demonstrated that FOXM1 and its target gene PLK1 are coordinately overexpressed in a proportion of gastric adenocarcinomas." (PMID 26576650, 2015). "In the current study, we investigate the expression of FOXM1 and PLK1 in gastric adenocarcinomas with particular emphasis on examining whether there is evidence that FOXM1and PLK1 are co-ordinately expressed." (PMID 26576650, 2015). "In this study we have demonstrated that FOXM1 protein, and PLK1 and FOXM1 mRNA levels are all markers of gastric adenocarcinoma when compared to normal gastric tissue." (PMID 26576650, 2015). "The expression levels of both PLK1 and FOXM1 mRNA are higher in gastric adenocarcinoma tissue compared to gastric tissue from healthy controls." (PMID 26576650, 2015). "We aimed to assess the expression of PLK1 and FOXM1 in Gastric adenocarcinomas in a Western Population, to examine whether there is a relationship of PLK1 to FOXM1 in cancer samples." (PMID 26576650, 2015). "Whilst our results suggest that both PLK1 and FOXM1 are implicated in carcinogenesis in gastric adenocarcinoma, blockade of one regulatory pathway is unlikely to halt cancer progression and induce widespread apoptosis in vivo." (PMID 26576650, 2015).
laryngeal squamous cell carcinoma (4 papers, 2020 to 2025). A squamous cell carcinoma that arises from the larynx. "Similarly, targeted inhibition of PLK1 inhibited the proliferation of laryngeal squamous cell carcinoma and decreased resistance to cisplatin." (PMID 39353904, 2024). "Besides, SKA3 overexpression facilitated proliferation and chemoresistance of laryngeal squamous cell carcinoma (LSCC) by reprogramming PLK1–AKT axis-mediated glycolytic metabolism, which was also related to the unfavorable prognosis of LSCC patients." (PMID 34845974, 2021). "Additionally, as a tumor metabolic regulatory gene, SKA3 can inhibit the ubiquitination and degradation of polo-like kinase 1 (PLK1) protein, resulting in the upregulation of glycolytic enzymes and enhanced glycolysis in laryngeal squamous cell carcinoma." (PMID 41298345, 2025).